BGN (biglycan)
Diseases named in the same sentence as BGN in open-access papers (continued):
Sharing a sentence is not in itself a finding about the gene and the disease.
gastric cancer (continued). "More importantly, celastrol down-regulated biglycan (BGN) protein, which is critical for gastric cancer migration and invasion." (PMID 31739592, 2019). "We herein identified a large number of genes associated with the ECM and cell adhesion to be differentially expressed in intestinal gastric cancer, including TIMP1, MMP7, FN1, SPARC, LUM and BGN, which were upregulated." (PMID 29484116, 2018). "Biglycan (BGN), an important component of the extracellular matrix, is overexpressed in gastric cancer tissues and promotes cancer metastasis." (PMID 28350359, 2017). "The best three single-gene discriminators are SERPINH1, BGN and COL12A1 for stomach cancer, having 99.1%, 98.2% and 98.2% classification accuracy on the training set and 94.2% and 96.7%, 88.4% and 93.3%, and 84.1% and 75.8% on the two test sets, respectively." (PMID 21060876, 2010). "For early stomach cancer, the best three 1-gene discriminators are also SERPINH1, BGN and COL12A1, respectively." (PMID 21060876, 2010). "In conclusion, the mutual interaction between tumor cells and activated MCs mediated by a BGN/FAP-STAT3 positive feedback loop facilitates PM of GC, providing a poor prognostic factor which could contribute to peritoneal metastasis of gastric cancer." (PMID 36632455, 2023). "This study shows that mutual interaction between tumor cells and activated MCs mediated by a BGN/FAP-STAT3 positive feedback loop facilitates PM of GC, providing a poor prognostic factor which could contribute to peritoneal metastasis of gastric cancer." (PMID 36632455, 2023). "First, we found that COL5A2, COL12A1, BGN and THBS2 were highly expressed in gastric cancer." (PMID 36447214, 2022). "In endothelial cells, Biglycan (BGN), a protein from the extracellular matrix, interacts with TLR2 and TLR4, leading to an increase in the HIF-1α activity, including VEGF overexpression, which in turn promotes gastric cancer progression and metastasis." (PMID 35565420, 2022). "The results showed that 8 up-regulated genes (FN1, COL3A1, FBN1, BGN, COL5A2, THBS2, COL5A1 and SPARC) and 1 down-regulated gene (ATP4A) may be the central genes in gastric cancer." (PMID 32742441, 2020). "Taken together, we identified celastrol as a necroptosis inducer, activated RIP1/RIP3/MLKL pathway and suppressed the level of pro-inflammatory cytokines by down-regulating BGN in HGC-27 and AGS cells, which supported the feasibility of celastrol in gastric cancer therapy." (PMID 31739592, 2019). "In this study, a total of 971 DEGs and 15 hub genes were selected, and BGN, MMP2, COL1A1 and FN1 might be the core genes of gastric cancer." (PMID 29050278, 2017). "We first examined the expression of BGN using qRT-PCR in gastric cancer and adjacent non-tumor tissues." (PMID 24681892, 2014). "Finally, it can be mentioned that, with the help of continuous bioinformatics analyses, BGN, LOX, MMP-9, SERPINE1, and TGFB1 proteins enhance the progression of gastric cancer; they play a significant role in the organization and communication of cells in the extracellular matrix." (PMID 34054953, 2021). "Intersection genes TREM2, CTHRC1, BGN, NOX4, GPX3, HEYL, and SFRP4 from the GSE72305 and GSE103236 datasets, which were differentially expressed in the normal gastric mucosa than in gastric cancer cells and in lymph node free to lymph node metastatic GC." (PMID 33976737, 2021). "We performed Quantitative Real-time PCR (qPCR) on 6 up-regulated genes (COL1A, BGN, SPP1, MELK, IGFBP4, SPARC) and 4 down-regulated genes (PGC, SST, MT1X, S100P) to verify our data in gastric cancer tissues (Tumor) and noncancerous tissues (Normal)." (PMID 25928635, 2015).
colon cancer (27 papers, 2010 to 2024). "The most significant signatures associated with colon cancer metastasis were determined to be BGN and THBS2." (PMID 36377223, 2022). "We next explored the association between BGN expression levels and outcomes of colon cancer patients in TCGA and GEO database." (PMID 35096572, 2021). "Conversely, in our study, high expression of BGN was proved to be implicated in the repression of both innate and adaptive immune responses in colon cancer." (PMID 35096572, 2021). "Our results manifested that higher BGN expression was linked to poorer overall survival (OS) in patients with colon cancer in TCGA (p = 0.007) and GSE17536 dataset (p < 0.001)." (PMID 35096572, 2021). "Further investigation revealed that BGN was strongly expressed in the immunosuppressive phenotype and tightly associated with the infiltration of multiple immune cells in colon cancer, especially M2 macrophages and induced Tregs." (PMID 35096572, 2021). "The association between BGN expression levels and immune cell infiltration in colon cancer was explored." (PMID 35096572, 2021). "Next, we utilized the CIBERSORT method to validate the association of BGN expression and immune components by constructing 22 types of immune cell profiles in colon cancer and analyzed the proportion of TIICs." (PMID 35096572, 2021). "We examined the effect of diabetes-associated factors on biglycan expression in HT29 human colon cancer cells." (PMID 32821344, 2020). "Association between BGN expression and clinicopathological factors of colon cancer patients." (PMID 35096572, 2021). "BGN regulates various signaling pathways such as the p38 signaling pathway in colon cancer cells and PI3K-Akt-NFκB pathway in retinoblastoma cells." (PMID 35053617, 2022). "The expression of BGN in colon cancer cells is induced by high sugar concentration, fatty acids, and insulin, and its contact co-culture with mesenchymal stem cells." (PMID 36358747, 2022). "Meanwhile, BGN is overexpressed in colon cancer stem cells and activates NF‐κB pathway, which leads to chemotherapy resistance, and BGN knockdown enhanced the HT‐29 cells' sensitivity to 5‐FU treatment." (PMID 36377223, 2022). "Eight significantly over‐expression genes in tumour tissues (BGN, THBS2, SPARC, CDH11, MFAP2, MMP11, SPP1 and THY1) were defined as significantly signature genes that implicated in colon cancer metastasis progress." (PMID 36377223, 2022). "BGN expression demonstrated a statistically significant upregulation in colon cancer tissues than in normal tissues." (PMID 35096572, 2021). "BGN is an encouraging predictor of diagnosis, prognosis and immunotherapeutic response in patients with colon cancer." (PMID 35096572, 2021). "First, sample data were obtained from public sources as a result of lacking adequate clinical information to verify the prognostic impact of BGN and its predictive value on immunotherapy response in patients with colon cancer." (PMID 35096572, 2021). "We compared the mRNA expression levels of BGN among 435 colon cancer samples and 41 normal samples in TCGA." (PMID 35096572, 2021). "Another observation that links biglycan signaling to the regulation of cancer cell proliferation was reported in a study conducted in HCT116 colon cancer cells." (PMID 34917515, 2021). "The relevance between clinical outcomes and BGN expression levels was evaluated using data from the GEO database, TCGA and tissue microarray of colon cancer samples." (PMID 35096572, 2021). "For instance, it was shown that, in colon cancer cells, inhibiting biglycan results in increased expression of pro-apoptotic effectors and is linked to suppressed NF-κB pathway activity." (PMID 34917515, 2021). "Colon cancer samples with high BGN expression (n = 5) and low BGN expression (n = 5) were used for IHC analyses." (PMID 35096572, 2021). "In HCT116 colon cancer cell line, BGN knockdown inhibited the proliferation and invasion (Xing, Gu, & Ma, 2015)." (PMID 31612481, 2020).
colon cancer (continued). "Biglycan knock-out led tumor cell apoptosis by decreasing cyclin A and cyclin D1 expression in colon cancer." (PMID 32825245, 2020). "Biglycan is highly expressed in colon CSCs and promotes chemoresistance of colon cancer cells by activating NF-kB signaling." (PMID 31334229, 2019). "Recent studies showed that BGN is elevated in tumor tissues such as colon cancer, and increased BGN expression is correlated with poor prognosis." (PMID 28525375, 2017). "Likewise, others also reported that knockdown of BGN in colon cancer cells depicted reduced proliferation, migration, invasion and enhanced apoptosis by upregulating the expression of p21 and p27." (PMID 35053617, 2022). "Indeed, biglycan is shown to upregulate VEGF expression in colon cancer cells and promote tumor angiogenesis." (PMID 35267503, 2022). "It is suggested that these hallmark genes (BGN, THBS2) may not only be novel EMT indicators but also provide direction for several clinical medications utilized in colon cancer treatment." (PMID 36377223, 2022). "Furthermore, in agreement with previously published findings, we discovered the average mRNA expression of BGN was higher in colon cancer tissues comparing with normal tissues in TCGA as well as in our own sample set." (PMID 35096572, 2021). "Several studies have focused on the role of biglycan in colon cancer." (PMID 34917515, 2021). "In patients with colon cancer, the transcriptional levels of BGN were markedly upregulated." (PMID 35096572, 2021). "Furthermore, the decreased biglycan levels suppressed colon cancer cell migration and invasion, and induced apoptosis in a p38 and MAPK-dependent manner." (PMID 34917515, 2021). "Moreover, in studies with colon cancer cell lines, BGN has been found to play an important role in proliferation, migration and invasion, along with the fact that it exerts an antiapoptotic effect." (PMID 34440771, 2021). "Finally, we demonstrated that high BGN expression presented a better immunotherapeutic response in colon cancer patients." (PMID 35096572, 2021). "Accordingly, BGN may be involved in initiation and maintenance of M2 polarization in macrophages of colon cancer." (PMID 35096572, 2021). "Moreover, biglycan-mediated chemotherapy resistance in colon cancer cells occurs by activating NF-κB signaling." (PMID 34917515, 2021). "In summary, this study provides preliminary evidence that BGN could serve as a valid biomarker for diagnosis, prognosis, and immunotherapy response prediction in patients with colon cancer." (PMID 35096572, 2021). "The present investigation suggests that BGN might act as a potentially essential modulator of macrophages in colon cancer, which is evidenced by quanTIseq and CIBERSORT analysis of the proportion of TIICs." (PMID 35096572, 2021). "Interestingly, in our study, we found a contrasting correlation between these two subpopulations of Treg cells and BGN expression in colon cancer, with iTregs showing a positive trend distribution with BGN expression." (PMID 35096572, 2021). "Extensive studies have elucidated the crucial role of BGN in regulating the progression and metastasis of various malignancies, including prostate, gastric, endometrial, and colon cancers." (PMID 33362844, 2020). "Instead of TLR2 or TLR4, BGN (which is significantly increased in colon cancer) may be a more useful marker in human colorectal cancer." (PMID 32050430, 2020). "Administration of shRNAs for BGN downregulated mRNA of BGN in colon cancer cells." (PMID 32050430, 2020). "The introduction of shRNA for BGN could restore immunosuppressive Siglec-7 ligand and its binding activity in colon cancer cells." (PMID 32050430, 2020). "Additionally, the administration of shRNAs for BGN led to the expression of normal glycans on colon cancer cells." (PMID 32050430, 2020). "BGN expression tends to increase in different cancers, and colon cancer expresses most." (PMID 32050430, 2020).
colon cancer (continued). "In addition, overexpression of at least two peptides corresponding to CD166, CD44, CD29, CEACAM5, biglycan, and cadherin 17 was detected in the colon tumour spheres." (PMID 20332776, 2010). "However, the role of BGN in colon cancer metastasis is less well investigated." (PMID 36377223, 2022). "In addition, our results reaffirm that BGN could serve as a potential informative molecule in the prognosis of colon cancer." (PMID 35096572, 2021). "Furthermore, BGN has been reported to promote the chemotherapy resistance via activating nuclear factor kappa‐light‐chain‐enhancer of activated B cells signal transduction in colon cancer (Liu, Xu, Xu, Cui, & Xing, 2018)." (PMID 31612481, 2020). "Five genes (BGN, THBS2, SPARC, CDH11 and SPP1) were initially identified as potential biomarkers and therapeutic targets of colon cancer metastasis." (PMID 36377223, 2022). "BGN binds to TLR4 and activates the NF-κB pathway in colon cancer cells, leading to epigenetic silencing of immunosuppressive siglec-7 ligand glycans." (PMID 35053617, 2022). "In the future, it is necessary and logical to investigate the function and mechanism of these potential signature genes (BGN and THBS2) for colon cancer metastasis using an experimental animal model and patients derived tumour cells." (PMID 36377223, 2022). "It is also proposed the potential action model of BGN and THBS2 regulating EMT and metastasis processes in colon cancer cells." (PMID 36377223, 2022). "It is thought that BGN and THBS2 overexpression contributes to the abnormality of colon cancer cells." (PMID 36377223, 2022). "IHC staining results indicated that BGN and THBS2 were significantly up‐regulated in most of the colon cancer tissues than health adjacent tissues." (PMID 36377223, 2022). "For instance, biglycan-induced, upregulated VEGFA expression promotes neovascularization and cancer growth in colon cancer cells." (PMID 34917515, 2021). "The response rate to immunotherapy in colon cancer patients was predicted by the ImmuCellAI and TIDE algorithms, both of which revealed that patients with high expression levels of BGN expression tended to be more likely to respond to immunotherapy." (PMID 35096572, 2021). "For example, high levels of biglycan triggered angiogenesis by upregulation of VEGF and the TLR signaling pathway in colon cancer and gastric cancer." (PMID 32825245, 2020). "We identified that BGN, S100A8, S100A9, and TNC expression levels were elevated significantly in colon cancer samples." (PMID 32050430, 2020). "Overexpression of biglycan has been reported in spheroids of CD133-positive cancer cells, and overexpression in colon cancer stem cells is considered to induce anticancer drug resistance." (PMID 32821344, 2020). "In human colon cancer cell line HT29, biglycan expression was induced by high sugar concentration, fatty acids, and insulin, and its contact co-culture with MSCs resulted in enhanced stemness and epithelial-mesenchymal transition phenotype." (PMID 32821344, 2020). "Previously, we showed that the introduction of shRNAs for BGN decreased NF-κB activity and restored immunosuppressive Siglec ligand expression by decreasing PRC2 activity in cultured colon cancer cells." (PMID 32050430, 2020). "BGN, COL1A1, and SFRP2 were upregulated DEGs at 1-cm tissue in our study and these three DEGs were present in the stromal gene group of Connell model related to colon cancer recurrence." (PMID 38062443, 2023). "Therefore, AEBP1, BGN, and TAGLN have been identified as potential biomarkers related to the response to FOLFIRI treatment of colon cancer." (PMID 36523769, 2022). "In addition, the gene expression levels of AEBP1, BGN, and TAGLN were negatively correlated with OS and DFS in colon cancer patients." (PMID 36523769, 2022). "It is strongly suggested that decreased expression of these genes (BGN, THBS2) could block the dominant signalling molecules in colon cancer metastasis." (PMID 36377223, 2022).
colon cancer (continued). "BGN and THBS2 knockdown significantly reduced colon cancer cells migration and invasion, as well as down‐regulating three EMT‐related proteins (Snail, Vimentin and N‐cadherin), and increasing the proliferation inhibitory effect of 5‐fluorouracil, irinotecan and oxaliplatin treatment." (PMID 36377223, 2022). "Furthermore, BGN enhances cancer cell stemness and EMT by affecting the interaction between cancer cells and mesenchymal stem cells during liver metastasis of colon cancer cells." (PMID 36358747, 2022). "Collectively, BGN might be a promising indicator for quantifying the TME and predicting the response to ICB immunotherapy in colon cancer." (PMID 35096572, 2021). "Moreover, correlation analysis demonstrated that BGN expression correlated with the immune score, stromal score and ESTIMATE score (Pearson r = 0.474, 0.733 and 0.648, respectively, all p < 0.001) in colon cancer." (PMID 35096572, 2021). "As a result, the immune response regulated by a series of immune cells tended to be “suppressive” with increasing of BGN expression, implying that BGN might also be involved in a negative interaction with the immune responses of colon cancer." (PMID 35096572, 2021).